IL6 (interleukin 6)
Diseases named in the same sentence as IL6 in open-access papers (continued):
Sharing a sentence is not in itself a finding about the gene and the disease.
type 1 diabetes (continued). "Additionally, an IL-6-inducible autoimmunity-related gene (HIP/PAP) was found to be expressed in the pancreas in patients with type-1 diabetes further indicating a potential correlation between IL-6 and autoimmune diabetes." (PMID 28484449, 2017). "In type 1 diabetes patients, elevated adiponectin levels may mediate the induction of interleukin-6 (IL-6), MCP-1, and IL-8." (PMID 25525608, 2014). "We also investigated the regulatory effect of type 1 diabetes on the transcription of genes related to inflammation such tumor necrosis factor-alpha (TNFα), interleukin-6 (IL6), monocyte chemotactic protein 1 (MCP1) and plasminogen activator inhibitor 1 (PAI1)." (PMID 25170835, 2014). "The previously published data on serum IL-6 level in type 1 diabetes are contradictory." (PMID 23533301, 2013). "In conclusion, one may suspect that the higher level of IL-6 seen in type 1 diabetic patients affects the quantitative and qualitative features of Treg/Th17 shifting the balance towards inflammatory Th17 cells." (PMID 23533301, 2013). "Our work shows the dysregulated balance of Th17 and Tregs in patients with type 1 diabetes, which may partly depend on impaired IL-6 signalization." (PMID 23533301, 2013). "Indeed, the levels of IL-6 observed in this group of BTHS patients were similar to those reported in children with Type I diabetes mellitus, suggesting the contribution of a low-grade inflammatory process." (PMID 22721508, 2012). "In support of the value of this approach, we replicated our previous findings in adolescents with Type 1 diabetes, observing elevated levels of all five inflammatory markers chosen for our risk score, but no observable differences in IL-6 or TNF-α levels (P = 0.851 and 0.224; data not shown)." (PMID 30863865, 2019). "However, IL-6 was not proven to be a cause of type-1 diabetes because there were many other proteins that serve as regulatory factors on the pancreatic beta cells." (PMID 28149833, 2017). "Therefore, we aimed to analyze the levels of cytokines, IL-6, TNF-α, VEGF, and IL-10, in serum of girls with type 1 diabetes and find out whether estrogen receptor α polymorphism has relevance for their production." (PMID 24523574, 2014). "In addition, we and others have shown the elevated serum IL-6 level in patients with type 1 diabetes which may play an important role in pathogenesis of diabetic microvascular complications." (PMID 23533301, 2013). "A recent clinical study tested the effects of two different monoclonal antibodies (mAbs) (siltuximab, anti-IL6; tocilizumab, anti-IL6R) on the fate and function of T-cells in people with type 1 diabetes." (PMID 41959136, 2026). "Elevated inflammatory cytokines, including TNF-α, IL-6, IFN-α, IL-1β, IFN-γ, IL-10, IL-12, and MIP-1β, have been observed after consumption of a high-fat meal in both individuals with type 1 diabetes (T1D) and healthy individuals." (PMID 40216734, 2025). "Our findings support the targeting of IL-2, IL-6 and TYK2 signalling in prevention of type 1 diabetes." (PMID 39271518, 2024). "However, since IL6ST expression in CD4+ and CD8+ naive or central memory T cells co-localised with type 1 diabetes and IL6R expression did not, it is tempting to speculate that trans-signalling might be more important than classic IL-6 signalling in the pathogenesis of type 1 diabetes." (PMID 39271518, 2024). "In individuals with longstanding type 1 diabetes, gene expression level was increased by 47% for TLR4 (p = 2.90 × 10−2, 95% CI −0.29, −0.01) and 36% for IL6 (p = 1.30 × 10−2, 95% CI −0.18, −0.02)." (PMID 33973017, 2021). "In vitro treatment with 1,25(OH)2D3 reduced proinflammatory cytokines (IL-6, CCL-2, IL-23A, IL-15) whereas anti-inflammatory cytokines (IL-10 and PD-L1) rose both in APS-type 1 diabetes and APS-Addison ́s disease." (PMID 33365026, 2020).
type 1 diabetes (continued). "The STZ-induced type 1 diabetic rats showed a significant increase of serum MDA (270 ± 13.4%, p ≤ 0.0001) and IL-6 (153 ± 2.70%) when compared to the normal control group." (PMID 30285704, 2018). "For most of the genes analyzed, transcripts levels were markedly decreased in response to type 1 diabetes except PPARγ and TNFα in eWAT, MCP1 in scWAT and PPARγ, IL6 and TNFα in rWAT." (PMID 25170835, 2014). "These included IL-6 signaling, IL-10 signaling, TREM1 signaling, MIF regulation of innate immunity, type I diabetes mellitus signaling, p38 MAPK signaling, toll-like receptor signaling, and acute phase response signaling." (PMID 21777429, 2011). "In contrast, liraglutide treatment reduced the level of IL‐6 in type 1 diabetic patients but did not improve the function of neurons." (PMID 37795833, 2024). "Interestingly, in humans, senescent beta cells accumulated prior to onset of Type 1 diabetes as seen by the increased expression of CDKN1A (p21), IL-6 and SERPINE-1 in pancreas from autoantibody-positive donors as compared to non-diabetic control donors." (PMID 37822597, 2023). "Interestingly, senescent beta cells accumulated prior to onset of Type 1 diabetes, seen as increased of CDKN1A, IL-6 and SERPINE-1 in autoantibody-positive donors as compared to non-diabetic control donors." (PMID 37822597, 2023). "In patients with type 1 diabetes and healthy individuals hypoglycaemia increases concentrations of several circulating molecules, including PAI-1, vascular endothelial growth factor (VEGF), VCAM, ICAM, E-selectin, P-selectin and IL-6." (PMID 35596173, 2022). "However, we previously found that subjects with LADA had distinct cytokine profiles compared with subjects with type 2 diabetes and type 1 diabetes regarding lipocalin 2 (LCN2), adiponectin, IL-6, and high-sensitivity C-reactive protein (hs-CRP)." (PMID 36090989, 2022). "In addition, the topical application of propolis on diabetic wounds has reduced/declined IL-1β, IL-6, TNF-α, and MMP9 levels in STZ-induced type I diabetic mice." (PMID 35047540, 2021). "Furthermore, as with the STZ-induced model of type 1 diabetes, myocardial tissue of db/db mice showed increased levels of TNF-α, IL-6, and MD2 levels compared with db/m controls." (PMID 32358497, 2020). "In addition to ameliorating renal inflammation as shown by mitigated NF-κB activities and IL-6 levels, EMP reduced glomerular hyperfiltration and urinary albumin excretions in the Akita mice model of type 1 diabetes." (PMID 31168342, 2019). "This group found that coculture significantly increased the TGF-β, IL-10, IL-6, and PGE2 cytokine levels and skewed toward Foxp3+ regulatory T cells, suggesting a switch to anti-inflammatory T helper 2 (Th2) signaling in a type 1 diabetes model treated with hBM-MSC-EVs." (PMID 30923617, 2019). "TAF5L, PDCD1, TCF7, IL6 and ICAM1 may be amongst the numerous loci with small effects in type 1 diabetes." (PMID 18045485, 2007). "However, there have been no studies yet that linked inflammatory biomarkers CRP, IL-6, IL-10, TNF-α, and NF-κB in saliva from adult individuals with type 1 diabetes with and without microvascular complications." (PMID 35788667, 2022). "In 543 patients divided into two groups based on the presence or absence of any complication of type 1 diabetes, circulating levels of C-reactive protein, interleukin-6, and tumor necrosis factor-α were increased in individuals with complications compared with those without." (PMID 29910771, 2018). "Moreover, monocytes isolated from patients with type 1 diabetes also present a proinflammatory phenotype and secrete higher levels of inflammatory cytokines, such as IL-6 and IL-1β, compared with nondiabetic individuals." (PMID 29850615, 2018). "In Caucasians with and without type 1 diabetes, a variant rs579459 near the ABO blood group gene accounted for 19% of the variance in E-selectin levels; in our GWAS, this same variant was associated with IL-6 levels (p = 1.7E-07)." (PMID 23251661, 2012).
type 1 diabetes (continued). "Additionally, the most significant canonical pathways were IL-6 signaling, IL-10 signaling, TREM1 signaling, MIF regulation of innate immunity, type I diabetes mellitus signaling, p38 MAPK signaling, toll-like receptor signaling, and acute phase response signaling." (PMID 21777429, 2011).
atopic dermatitis (123 papers, 2011 to 2026). "The reduction in IL-6 by SBEIEs is particularly significant, as IL-6 overexpression has been linked to oxidative stress-driven skin disorders, including acne and atopic dermatitis." (PMID 40227405, 2025). "Chronic inflammation is characteristic of atopic dermatitis, primarily caused by increased levels of pro- inflammatory cytokines such as IL-6 or TNF-alpha." (PMID 38892934, 2024). "Published data show that the over expression of Th2 cytokines is prevalent in the acute phase of lesions caused by atopic dermatitis, while in the meantime, other proinflammatory cytokines, such as IL-6 and TNF-α, are over expressed in the chronic phase." (PMID 35883395, 2022). "Application of dTBP2 inhibited the mRNAs levels of proinflammatory cytokines such as IL-6 well as Th2-related cytokines/chemokines associated with pathogenesis of atopic dermatitis including IL-4, IL-5, IL-13, TSLP, MCD, and TARC." (PMID 28134765, 2017). "IL-6 has also been implicated in atopic dermatitis and can regulate T cell differentiation." (PMID 33104726, 2020). "Levels of IL-12 and IL-6 cytokines were significantly increased, which could explain the increased inflammation in the skin of patients with atopic dermatitis who presented this TLR2 mutation." (PMID 31781672, 2019). "In atopic dermatitis, chronic elevation of cytokines such as IL-4, IL-13, and IL-6 perpetuates a Th2-skewed immune response that extends beyond the skin, leading to persistent systemic inflammation." (PMID 41465136, 2025). "Chronic Th2-skewed inflammation in atopic dermatitis, characterized by sustained IL-4, IL-13, and IL-6 signaling, can disrupt the BBB, promote microglial activation, and induce neuroinflammatory cascades that impair Aβ clearance." (PMID 41465136, 2025). "Atopic dermatitis is characterized by the overproduction of pro-inflammatory cytokines (such as IL-1β, IL-6, IL-8)." (PMID 40563511, 2025). "As a chemokine, thymus and activation-regulated chemokine (TARC) plays an imperative role in the homing of skin-specific T cells, whereas IL-8 and IL-6 are involved in the recruitment of various cells into atopic dermatitis skin." (PMID 38541664, 2024). "SF-7343 (King George Island, Antarctica), and it inhibited the secretion of IL-8 and IL-6 in tumor necrosis factor-α/interferon-γ-treated HaCaT cells in an inflammatory disease, atopic dermatitis." (PMID 39452841, 2024). "Ethanol extract of A. millefolium (50%) reduced the expression of pro-inflammatory cytokines, such as iNOS, COX-2, and IL-6 in lipopolysaccharide (LPS)-treated murine macrophage Raw 264.7 cells, indicated anti-atopic dermatitis activity of the plant." (PMID 40255946, 2024). "Our previous results showed that histamine increases the secretion of the pro-inflammatory cytokines IL-1α, IL-6 and IL-8 in our atopic dermatitis skin models m2 and m3, when added at day 9 to the medium." (PMID 36615633, 2023). "Previous studies reported the anti-inflammatory and immunomodulatory effect of diosmin on the skin keratinocytes in other dermatological diseases such as atopic dermatitis via modulation of Th2 cells activity and the inflammatory cytokines such as IL6 and IL1." (PMID 37010718, 2023). "In DNCB-induced atopy mouse model, illumination with visible red (650 nm) alleviates symptoms of atopic dermatitis and restores cytokine levels such as IL-6 and TNF-α to normal." (PMID 36979014, 2023). "ASX reduced the gene expression of many proinflammatory indicators in an atopic dermatitis model, including interleukin-1 (IL-1), interleukin-6 (IL-6), and tumor necrosis factor-ɑ (TNF-ɑ)." (PMID 38256329, 2023). "Elevated levels of IL-6 compared to healthy controls were only measured when histamine was added at day 9 to atopic dermatitis skin model m3 and healthy skin model m4." (PMID 36615633, 2023).
atopic dermatitis (continued). "TNF-α/IFN-γ, which is extensively employed in atopic dermatitis simulations, acts on HaCaT cells and induces them to release chemokines and cytokines, such as IL-6, IL-8, CCL17, and CCL22." (PMID 37110740, 2023). "The proinflammatory cytokine IL-6 is produced in keratinocytes facing barrier disruption or chemicals, and is related to eczematous dermatitis." (PMID 36012891, 2022). "SIG-1451, a novel non-steroidal anti-inflammatory drug candidate being developed for the treatment of atopic dermatitis, was found to inhibit lipopolysaccharide (LPS)-induced IL-6 production." (PMID 35955937, 2022). "The levels of IL-4, IFN-γ, and IL-6 significantly increase in the dorsal skin of animals with inflammatory diseases such as atopic dermatitis." (PMID 35222003, 2021). "NF-κB and the subsequent production of IL-6 were also shown to be downregulated in mice with TPA-induced atopic dermatitis, when they were treated with Glycyrrhiza glabra, a direct inhibitor of HMGB1, one of the main ligands of RAGE." (PMID 33435332, 2021). "Mast cell-mediated inflammatory cytokines (e.g., TNF, IL-1, IL-4, and IL-6) occur as part of the tissue remodeling related to atopic dermatitis and allergic asthma, and in many other scenarios characterized by chronic allergic inflammation." (PMID 32932637, 2020). "Further, in an oxazolone-induced atopic dermatitis model, the expression of IL-6 was significantly decreased in skin samples from TRPA1 KO mice compared to WT mice." (PMID 33374841, 2020). "Oclacitinib, an FDA-approved JAK inhibitor for the treatment of atopic dermatitis in dogs, blocks IL-6 signaling and subsequent STAT3 phosphorylation at recommended dosing, thus represents a viable approach to targeting STAT3 in veterinary cancer patients." (PMID 31409327, 2019). "They reported that treatment of atopic dermatitis mouse model with ZnO NPs suppresses local inflammation by down-regulation of the expression levels of pro-inflammatory cytokines such as IL-1β, IL-6, and TNF-α." (PMID 30127816, 2018). "Atopic dermatitis increased the expression levels of IL-4, IL-13, IL-6, IL-17, IFNγ, and TNFα but decreased the expression of IL-10 in BALB/c mouse, in an SOCS1-dependent manner." (PMID 30459600, 2018). "This activation or enhancement of gene expression increases secretion of IL-6 and Th2 cytokines, and which in turn promotes the development of allergic dermatitis in mice." (PMID 28240277, 2017). "Innovative efforts were undertaken in models for atopic dermatitis by exploiting mediators previously correlated with atopic dermatitis, such as IL-23, or using IL-6 for biomonitoring atopic dermatitis [12▪▪]." (PMID 28375932, 2017). "Th17 cytokine (IL-17 and IL-22) upregulates the expression of CXCL8 and IL-6 in the skin of atopic dermatitis patients and promotes inflammation of the skin." (PMID 28558005, 2017). "This goes align with the restriction impact of PD98059 on IL-6, NF-κB in an atopic dermatitis model, beside other studies documented the neuroprotective effect of PD98059 against BACE-1 expression in human SH-SY5Y neuroblastoma as well as Aβ precipitation in models of AD." (PMID 40381124, 2025). "Thus, keratinocytes from patients with atopic dermatitis present elevated mitosis and continuous production of pro-inflammatory factors with an abnormal release of cytokines such as IL-1, IL-6, TNF-α, MCP-1, RANTES, among others." (PMID 39408993, 2024). "In addition, the chemokines IL-6 and IL-8 attract inflammatory immune cells to the site of an atopic dermatitis." (PMID 38672764, 2024). "Furthermore, in patients with atopic dermatitis, the ability of regulatory B cells to produce IL-10 in response to IL-6 stimulation is diminished." (PMID 39767628, 2024).
atopic dermatitis (continued). "The fact that it effectively reduces the increase in TNF-α and IL-6 induced by lipopolysaccharide (LPS) stimulation in RAW264.7 cells, along with the significant decrease in TNF-α and IL-6 observed in an atopic dermatitis animal model, consistently aligns with the findings of our study." (PMID 37686078, 2023). "Chronic atopic dermatitis is caused by the release of cytokines such as TNF-α and IL-6." (PMID 35955937, 2022). "It is interesting to note that L. plantarum KCTC 11401BP EVs decreased IL-6 levels, protected cell viability of human epidermal keratinocytes (HaCaT) incubated with S. aureus EVs and reduced skin inflammation in S. aureus EV-induced atopic dermatitis in mice." (PMID 35432276, 2022). "In addition, L. plantarum-derived EVs reduce inflammatory responses in S. aureus-induced atopic dermatitis mice by suppressing IL-6 and IL-4." (PMID 33233771, 2020). "Furthermore, it was previously shown that L. plantarum-derived EVs suppress inflammatory responses in S. aureus-induced atopic dermatitis mice by blocking the secretion of IL-6 and IL-418." (PMID 32123288, 2020). "Also, interrupting IL-6 signaling has been shown to improve atopic dermatitis suggesting that IL-6 contributes to its pathogenesis." (PMID 31781680, 2019). "Another study investigated PBdMC from atopic eczema patient and observed higher total histamine and tryptase levels, impaired expression of fungal recognition receptor, and enhanced IL‐6 secretion after fungal stimulation from PBdMC obtained from atopic eczema subjects compared to healthy controls." (PMID 29992767, 2018). "It has consistently been shown that the mRNA levels of TNF-α and IL-6, which have been implicated in the pathogenesis of atopic dermatitis, are higher in atopic obese rats than in the nonobese ones." (PMID 28696379, 2017). "The chronic aspects in atopic eczema are accompanied by IL-6 induction." (PMID 28375932, 2017). "Postbiotics are known to suppress inflammatory markers, such as IL-1 and IL-6, support the structure of the stratum corneum through the action of short-chain fatty acids, and improve outcomes in inflammatory skin conditions, including atopic dermatitis, eczema, and acne." (PMID 41302077, 2025). "Furthermore, we examined the mRNA expression of IL-6 in TNF-α/IFN-γ-induced HaCaT cells to evaluate whether SHCGT dose-dependently affects the atopic dermatitis." (PMID 34616298, 2021). "Studies of atopic eczema have shown that the cellular component of Malassezia affects the expression of a C-type lectin receptor gene, dectin-1, which results in aggravation of the disease, as measured by increased IL-6/IL-8 gene expression and β-hexosaminidase, histamine, and tryptase release." (PMID 33014894, 2020). "Moreover, another report from the same group showed that S. aureus MVs produced proinflammatory mediators, such as interleukin-6, thymic stromal lymphopoietin, macrophage inflammatory protein-1α, and eotaxin, and induced atopic dermatitis-like skin inflammation." (PMID 22114730, 2011). "This aligns with previous studies demonstrating that IL-37b can inhibit the in vitro induction of pro-inflammatory cytokines (IL-6 and TNF-α) and chemokines (CXCL8, CCL2, and CCL5) related to atopic dermatitis." (PMID 40444012, 2025). "In atopic dermatitis models, ligustilide up-regulates filaggrin and SPTLC1, and reduces tumor necrosis factor-α (TNF-α), interferon-γ, and interleukin-6 (IL-6) to reinforce skin barrier function." (PMID 40904624, 2025). "The graph of Network Pharmacology Survey shows that the effect of silica and silver nanoparticles on the expression of various genes such as IL4, IL6, IL8 and TNFα leads to the occurrence of various skin diseases such as atopic dermatitis." (PMID 38454025, 2024).